BRCA1 (BRCA1 DNA repair associated)
Diseases named in the same sentence as BRCA1 in open-access papers (continued):
Sharing a sentence is not in itself a finding about the gene and the disease.
breast cancer (continued). "In the 3,361 BRCA1 mutation carriers in CIMBA, we observed a statistically significant inverse association with breast cancer risk (per-allele HR = 0.89, 95% CI 0.80–1.00, p = 0.048)." (PMID 22768030, 2012). "It is intriguing that MG132 alone induced a decrease in both HSF1 and BRCA1 protein levels in Triton-soluble fractions while inducing an increase in their levels in Triton-insoluble fractions of breast cancer cell protein extract." (PMID 25969759, 2012). "Comparative qPCR of ER+ and ERαKD cell lines was performed on a sample of relevant genes (ErbB2, BRCA1, PR, and of course ERα) to verify if the specific knockdown of ERα affected the expression of other breast cancer-related genes." (PMID 23140372, 2012). "Downregulation of EZH2 expression in breast cancer cells led to decreased proliferation, delayed cell-cycle transition, and upregulation of the BRCA1 protein." (PMID 23133536, 2012). "After counseling of the index patient and obtaining informed consent, analysis of the breast cancer genes BRCA1 and BRCA2 and testing for HNPCC was performed." (PMID 23164213, 2012). "The loss or reduction of BRCA1 expression, moreover, significantly reduces the TGF-beta induced activation of SMAD3 in breast cancer cells." (PMID 22646717, 2012). "Third, BRCA1-IRIS overexpression was associated with poor prognosis and outcome in breast carcinoma of the HER2+ and TN/BL subtypes." (PMID 22511931, 2012). "Carriers of mutations in the BRCA1 and BRCA2 genes are at very high risk of developing breast cancer (BC) and ovarian cancer." (PMID 22762150, 2012). "Mutations in BRCA1 and BRCA2 confer a high risk of breast cancer (BC), but the magnitude of this risk seems to vary according to the study and various factors." (PMID 22762150, 2012). "CIMBA database contains demographic, clinical and epidemiological data from 15,700 BRCA1 and 8,600 BRCA2, mutation carriers including 12,700 breast cancer patients, 2,500 ovarian cancer patients and 9,100 unaffected patients from 42 centers over the world." (PMID 21639959, 2011). "At this point, nothing is known regarding gemcitabine as a selective targeted agent in BRCA1 mutant breast cancers." (PMID 21771338, 2011). "To date, little is known about how pathogenic BRCA1 mutations that disrupt BRCT phospho-protein binding affect DSB repair and the pathophysiology of breast cancer." (PMID 21666281, 2011). "BRCA1 and BRCA2 mutations are quite penetrating: the cumulative risk of breast cancer is about 65% in BRCA1-mutation carriers (by age 70) and about 45% in BRCA2-mutation carriers." (PMID 22312537, 2011). "Invasive ductal carcinoma, NOS (not otherwise specified) type, is the most common histologic form of all hereditary breast cancers, including BRCA1- and BRCA2-associated breast cancers." (PMID 22295226, 2011). "For example, in a neoadjuvant setting with cisplatin, an 83% pathologic complete response rate in BRCA1 breast cancer carriers has been reported." (PMID 21989022, 2011). "While BRCA1 and BRCA2 mutations are highly penetrant, resulting in higher risk for breast cancer, both of these genes are also highly polymorphic." (PMID 21708019, 2011). "Decreased BRCA1 mRNA expression in a breast cancer cell line led to a greater sensitivity to cisplatin and etoposide and to a greater resistance to the microtubule-interfering agents paclitaxel and vincristine." (PMID 21157449, 2011). "Investigation of low BRCA1 expression in the human breast cancer cell line SK-BR-3 revealed a transcriptional network consisting of NRF-1 > GABPβ > BRCA1." (PMID 21609478, 2011).
breast cancer (continued). "Although high-penetrant susceptibility genes such as BRCA1 and BRCA2 demonstrate potent associations with the familiar breast cancer, many low-penetrant susceptibility genes predisposing to breast cancer remain to be elucidated." (PMID 21917182, 2011). "We found no study that showed a survival difference when BCT was compared to mastectomy in BRCA1/2 mutation carriers or when BCT was compared in BRCA1/2 mutation carriers and familial, non-BRCA1/2-associated breast cancer and/or sporadic controls." (PMID 22295226, 2011). "This issue was particularly intensively discussed in breast cancer research, owing to substantial overlap between BRCA1-related and triple-negative BC." (PMID 21819606, 2011). "The strength of this study lies using MBPC, a validated intermediate phenotype for breast cancer, as the dependent variable in EBV-immortalized cell lines from a large number of BRCA1 mutation carriers in order to assess genotype-phenotype associations." (PMID 21708019, 2011). "It has however been shown that approximately 10% of men with breast cancer carry BRCA2 mutations, while mutations in BRCA1 are exceedingly rare." (PMID 21949660, 2011). "MCF7 displayed the most significant level of BRCA1 protein expression of the breast cancer cell lines and was assigned a value of 1.0." (PMID 21854619, 2011). "The BRCA1 and BRCA2 tumor suppressor genes have been established as important high penetrance familial breast cancer susceptibility alleles." (PMID 21835029, 2011). "Decreased BRCA1 expression has been found in approximately 30–40% of sporadic breast cancers and 15–80% of ovarian cancers." (PMID 22312502, 2011). "BRCA1-related breast cancers have been described to share similarities with basal epithelial (basal-like) and triple-negative phenotypes." (PMID 22032724, 2011). "The preventive benefit of prophylactic BSO does appear to reduce the prevalence of breast cancer as well as to improve BCSS and to improve OS in premenopausal BRCA1/2 mutation carriers." (PMID 22295226, 2011). "In the context of breast cancers arising in young women, we found that any BRCA1 predictive value of these two measures appears to be subsumed by the two key morphological features." (PMID 21343941, 2011). "Upregulation of BRCA1 expression has also been shown to occur in response to 17β-estradiol in various breast cancer cell lines and in overectimized mice, and BRCA1 levels increase during puberty and pregnancy when estradiol levels peak." (PMID 21914189, 2011). "This compound displays potent PARP-1 and PARP-2 inhibition, and inhibits proliferation of breast cancer cells with mutant BRCA-1 and BRCA-2 with IC50 in the range of 10-100 nM." (PMID 21504625, 2011). "Poly (ADP-ribose) polymerase inhibitors (PARPi) are a novel therapeutic option for the treatment of ovarian and breast cancers which preferentially target BRCA1-defective cells and spare those with normal function." (PMID 22312502, 2011). "Families are being tested for mutations in BRCA1, BRCA2 and the other major breast cancer susceptibility genes." (PMID 21352566, 2011). "Breast cancer was diagnosed at an average of 6.8 years earlier in daughters in the BRCA1 families (p = 0.002)." (PMID 21829373, 2011). "The training set consisted of 39 BRCA1-likeaCGH breast cancers and 45 non-BRCA1-likeaCGH breast cancers, which had previously been analyzed by aCGH." (PMID 22032731, 2011). "We trained a shrunken centroids classifier on the training set and validation was performed on an independent test set of 40 BRCA1-likeaCGH breast cancers and 32 non-BRCA1-likeaCGH breast cancer tumours." (PMID 22032731, 2011). "Sequence variation in the BRCA1 gene accounts for 45 percent of inherited breast cancer and more than 90 percent of inherited breast and ovarian cancer, and both genes combined account for only 25 percent of familial risk." (PMID 21559243, 2011).
breast cancer (continued). "Currently known susceptibility genes including BRCA1, BRCA2, ATM, CHEK2, PALB2, RAD51C and BRIP1 explain less than 25% of familial breast cancer." (PMID 21774837, 2011). "The two major high-penetrance BrCa genes, BRCA1 (breast cancer 1) and BRCA2 (breast cancer 2), are responsible for 30% of hereditary breast cancer (HBC) cases worldwide, but only for about 20% in Finland." (PMID 21356067, 2011). "Mutations in BRCA1 (and BRCA2) confer a high risk for breast cancer, with a lifetime risk of up to 80%." (PMID 22032724, 2011). "Although there have been several studies that estimate the risk of contralateral breast cancer in women with a BRCA1 or BRCA2 mutation, there has been little research on the predictors of contralateral breast cancer risk." (PMID 21487411, 2011). "It raises the questions of c-Myc's involvement in the DNA methylation complex in breast cancer cells; particularly if BRCA1 is a target." (PMID 21668996, 2011). "We describe the first case of a patient with no strong family history of the disease who developed early-onset bilateral breast cancer with a de novo complete BRCA1 gene deletion in the germinal line." (PMID 21989022, 2011). "Our analysis of a limited number of samples did not reveal strong evidence of gene fusions as major contributors to the development of BRCA1 breast cancers." (PMID 22032724, 2011). "BRCA1-mutant HCC1937 breast cancer cells showed increased sensitivity to etoposide as compared to BRCA1-wild-type expressing isogenic cells, as shown by a clonogenic assay." (PMID 21819606, 2011). "We performed mutation analysis of BRCA1 and BRCA2 on 127 unselected patients with breast cancer in Athens, Greece." (PMID 22085629, 2011). "The last patient underwent prophylactic bilateral mastectomy because of strong family history of breast cancer and had tested positive for the BRCA1 gene." (PMID 21785684, 2011). "We have investigated gene and protein interactions in a centrosome-cantered module, including BRCA1/BRCA1 and HMMR/RHAMM, across biological systems ranging from breast cancer risk estimates to cellular phenotypes and cytoskeletal structures." (PMID 22110403, 2011). "For our population-based sample of women with early-onset breast cancer, if BRCA1 screening had been restricted to those with a strong family history then we would have screened 71 cases and found 10 carriers (14%)." (PMID 21343941, 2011). "In this report we show that c-Myc can activate BRCA1 expression in breast cancer cells, and depletion of c-Myc reduced BRCA1-dependent DNA repair." (PMID 21668996, 2011). "On the basis of these findings, we tested the efficacy of erlotinib for the primary prevention of breast cancer in BRCA1-mutant mice." (PMID 21396117, 2011). "BRCA1-mutant HCC1937 breast cancer cell line showed increased survival and decreased apoptosis in response 6-thioguanine as compared to BRCA1-wild-type expressing isogenic cells." (PMID 21819606, 2011). "The Brca1-/- MMECs have also been reported to harbor defective DNA base-excision repair as well as increased genetic instability compared to Brca1+/+ MMECs, which is typical of BRCA1-mutant breast cancer cells." (PMID 21771338, 2011). "In this respect, it has been demonstrated that BRCA1 inactivation in sporadic disease leads to development of basal/TNP breast cancers." (PMID 21958427, 2011). "To date, we have found no studies that show a statistically significant difference in BCSS or OS after a breast cancer diagnosis when BRCA1/2 carriers are compared with matched sporadic controls." (PMID 22295226, 2011). "In the present study, we describe a de novo deletion of BRCA1 in the germinal line of an early-onset breast cancer patient." (PMID 21989022, 2011).
breast cancer (continued). "For example, JARID1B was reported to transcriptionally regulate BRCA1 in breast cancer, via direct interaction with promoter sites." (PMID 21980403, 2011). "siRNA-directed inactivation of BRCA1 function in MCF7 breast cancer cells rendered resistance to paclitaxel-induced growth inhibition and mitotic arrest." (PMID 21819606, 2011). "In this report, we used cultured breast cancer cells to examine the mechanisms of transcriptional activation of BRCA1 by c-Myc." (PMID 21668996, 2011). "Loss of BRCA1 expression is a marker of tumour aggressiveness, potentially linked to BRCA1 status and a CSC phenotype in primary breast cancer." (PMID 23508738, 2011). "Inhibition of BRCA1 expression in HBL100 breast cancer cells led to increased sensitivity to cisplatin and etoposide, but resistance to paclitaxel and vincristine, as assessed by the rhodamine B proliferation test." (PMID 21819606, 2011). "Two major high-penetrance breast cancer genes, BRCA1 and BRCA2, are responsible for approximately 20% of hereditary breast cancer (HBC) cases in Finland." (PMID 21356067, 2011). "We report the first case of a patient with no strong family history of the disease, with a de novo complete BRCA1 gene deletion demonstrated by Array CGH that developed early-onset bilateral breast cancer." (PMID 21989022, 2011). "Thus, the data presented here could perhaps have clinical implications in that RAD51 and RPA might be useful diagnostic markers for pre-malignant (DCIS) breast cancers and, in particular, for screening breast cancers for mutations in the BRCA1 BRCT domain that result in hyper-recombination." (PMID 21666281, 2011). "EGFR overexpression appears to correlate with the basaloid phenotype and is found in 67% of BRCA1-related cancers versus only 18% of non-BRCA1-related breast cancers." (PMID 21396117, 2011). "In our study, increasing doses of the HDAC inhibitor M344 down regulated BRCA1 protein expression in all cell lines examined except for the highest dose in MCF7 breast cancer cells." (PMID 21854619, 2011). "Currently known susceptibility genes such as BRCA1 and BRCA2 explain less than 25% of familial aggregation of breast cancer, which suggests the involvement of additional susceptibility genes." (PMID 21774837, 2011). "In the present study, to evaluate the pattern of expression and prognostic significance of BRCA1 in breast tumours, we analysed the expression of the BRCA1 protein in a series of unselected breast cancer cases by immunohistochemistry." (PMID 23508738, 2011). "It has been shown empirically that the rare mutations in BRCA1 and BRAC2 associated with a 10-fold or more increased risk of breast cancer account for about a modest 1.2-fold increased familial risk, around 20% of population familial aggregation." (PMID 21352566, 2011). "In the current expanded cohort, we estimate the 10-year contralateral breast cancer risks to be 24% for BRCA1 carriers and 19% for BRCA2 carriers." (PMID 21487411, 2011). "In contrast to the findings with CD133+ positive cells from brain tumors, only slightly increased activation of downstream pathways was found primarily in BRCA1 although additional downstream targets of ATM in breast cancer CIC need to be examined." (PMID 21935375, 2011). "Overall, variable levels of BRCA1 mRNA and protein were detected in the ovarian and breast cancer cell lines analyzed which is consistent with the range of expression levels previously observed in ovarian and breast tumor specimens." (PMID 21854619, 2011). "Previous data from our lab and others have shown that BRCA1 expression in breast cancer was regulated at epigenetic and transcriptional levels." (PMID 21668996, 2011).
breast cancer (continued). "In breast tumours, the loss of nuclear expression was detected in 23 cases (15%), whereas cytoplasmic expression of BRCA1 was observed in 133 breast carcinomas (85%)." (PMID 23508738, 2011). "A range of regimes was used to treat 27 lymphoblastoid cell-lines (LCLs) derived from affected women in high-risk breast cancer families (nine BRCA1, nine BRCA2, and nine non-BRCA1/2 or BRCAX individuals) and nine LCLs from healthy individuals." (PMID 20174566, 2010). "HCC1937 is the BRCA1-defective breast cancer cell line and has a low sensitivity to paclitaxel and doxorubicin." (PMID 20579400, 2010). "Other PARP inhibitors are being studied; for example, AGO 14699 in locally advanced or metastatic breast cancer and BRCA1/2-mutated ovarian cancer, and AZD2881 in BRCA1/2-mutated ovarian cancer and metastatic TN or BRCA-mutated breast cancer." (PMID 21050424, 2010). "We provide evidence for a major role for BRCA1 mRNA expression as a marker of time to progression and overall survival in sporadic breast cancers treated with anthracycline-based chemotherapy." (PMID 20209131, 2010). "BRCA1 and BRCA2 mutations together were estimated to explain 32% of breast cancer FRR for ER-negative disease and 9.4% of FRR for ER-positive disease." (PMID 20146796, 2010). "In this work, we analyzed and compared aCGH data from a large series of mouse and human BRCA1- and BRCA2-mutated breast cancers, in order to obtain a complete collection of genes and loci that are recurrently gained or lost in tumors of both species." (PMID 20735817, 2010). "Instead, we estimated the contribution of BRCA1 and BRCA2 mutations to the breast cancer FRR by tumour subtype by modeling their effects in the risk prediction algorithm BOADICEA." (PMID 20146796, 2010). "Identifying genes whose expression is associated with BRCA1, BRCA2 and BRCAX mutation status would be a valuable method of screening individuals from multiple case breast cancer families for the presence of pathogenic mutations." (PMID 20174566, 2010). "The role of breast cancer related genes, BRCA1 and BRCA2, in the NHEJ pathway suggests that the mechanisms involved in DNA DSB repair are of particularly important during breast tumorigenesis." (PMID 20808786, 2010). "For counseling of women identified as having a double heterozygote for mutations in BRCA1 and BRCA2, the risk of transmitting a breast cancer susceptibility gene to any daughters is 3⁄4." (PMID 20579331, 2010). "Several models have been developed for predicting risk of carrying BRCA1 or BRCA2 mutation and subsequently developing breast cancer." (PMID 20482762, 2010). "Further, as BRCA1 carriers age, they are increasingly more likely to develop an ER+ breast cancer following the trend seen in breast cancers that develop in the general population." (PMID 21080930, 2010). "Larger sample sizes are necessary to determine if BRCA1 methylation occurs more frequently in particular types of breast cancer or in normal breast tissue." (PMID 20614009, 2010). "Over 2,000 unique BRCA1 and BRCA2 missense variants have been identified, located throughout the whole gene (Breast Cancer Information Core Database (BIC database))." (PMID 24281179, 2010).